TRIM42 (tripartite motif containing 42)
Synonyms: FLJ40097; PPP1R40; T4A1
Tractability: No criterion of Open Targets' tractability assessment is met for any kind of drug.
Gene: Protein-coding gene on chromosome 3 (140,678,064 to 140,701,150, forward strand). Ensembl gene ENSG00000155890.
Gene Ontology:
Molecular function: protein binding; ubiquitin protein ligase activity; zinc ion binding
Biological process: protein ubiquitination
Genetic constraint (gnomAD): Loss-of-function variants: 59 observed, 67.82 expected, observed/expected ratio (o/e) 0.87, 90% interval 0.7 to 1.08. The upper end of that interval is the gene's LOEUF score, 1.08, which puts it in group 4 of 6, group 1 being the genes least tolerant of losing a copy. Missense variants: 878 observed, 975.94 expected, observed/expected ratio (o/e) 0.9, 90% interval 0.85 to 0.95. Synonymous variants: 354 observed, 366.71 expected, observed/expected ratio (o/e) 0.97, 90% interval 0.88 to 1.05.
Homologues: Orthologues: chimpanzee TRIM42 (99% identical), macaque TRIM42 (97% identical), dog TRIM42 (90% identical), pig TRIM42 (89% identical), rat Trim42 (87% identical), mouse Trim42 (87% identical), rabbit TRIM42 (86% identical), guinea pig TRIM42 (86% identical). Paralogues in human: MID2 (15% identical), MID1 (15% identical), PML (14% identical), TRIM27 (14% identical), TRIM60 (13% identical), TRIM58 (13% identical), MEFV (13% identical), TRIM39 (12% identical), TRIM4 (12% identical), TRIM21 (12% identical), TRIM25 (12% identical), TRIM10 (12% identical), and 68 more.
Diseases named in the same sentence as TRIM42 in open-access papers:
TRIM42 is named in the same sentence as 1 disease in open-access papers, as found by Europe PMC text mining. Sharing a sentence is not in itself a finding about the gene and the disease. The quoted sentences say what the papers report.
melanoma (1 paper, 2020). A malignant, usually aggressive tumor composed of atypical, neoplastic melanocytes. "We noticed certain correlations between gene expression and events between LADs and inter-LADs—for example, a complex rearrangement in a melanoma sample coincided with a sevenfold upregulation of TRIM42 (which resides in a LAD) compared with the rest of the patients with melanoma." (PMID 32024999, 2020).